INSR (insulin receptor)
Diseases named in the same sentence as INSR in open-access papers (continued):
Sharing a sentence is not in itself a finding about the gene and the disease.
colorectal cancer (23 papers, 2011 to 2025). A primary or metastatic malignant neoplasm that affects the colon or rectum. "Nevertheless, a single study reported a miR-612 target site at the 3′UTR of the insulin receptor (INSR), and proposed a potential association of insulin receptor expression/insulin signaling with colorectal cancer." (PMID 23077621, 2012). "In a case-control association study of sporadic colorectal cancer, a genetic variation in the 3′UTR of insulin receptor (INSR) expression, corresponding to a miR-612 target site, was significantly associated with increased cancer risk." (PMID 23077621, 2012). "In addition, we experimentally validated predicted synergy of the BRAF/insulin receptor combination (Dabrafenib/BMS-754807) in 48 colorectal cancer cell lines." (PMID 32487991, 2020). "We identified insulin receptor (INSR) as a marker of the tumour vasculature in a genomic search analysing RNA preparations from isolated colorectal carcinoma (CRC) endothelial cells (EC) and their counterparts from normal colorectal tissue samples." (PMID 30559346, 2019). "We identified insulin receptor (INSR) as a specifically and highly overexpressed gene in the tumour vasculature of colorectal carcinoma (CRC) and validated this by qPCR." (PMID 30559346, 2019). "The results showed that, compared with normal tissues, the expression of ADRA1B, CDKN2A, FCER2, and IL13 was significantly upregulated in colorectal cancer tissues, while CALM1, CTNNA1, GSR, INSR, and MAPK9 were significantly downregulated." (PMID 40696679, 2025). "In colorectal cancer, PTPRN deletion impairs invasiveness and metastatic potential through dysregulated epithelial–mesenchymal transition (EMT) and insulin receptor signaling." (PMID 41295383, 2025). "Clinical trials on colorectal cancer patients largely failed when EVE was used as a single agent or combined with the anti-VEGF-A antibody bevacizumab or the insulin receptor/insulin-like growth factor R receptor inhibitor linsitinib for the treatment of refractory metastatic colorectal cancer." (PMID 34675191, 2021).
prostate carcinoma (23 papers, 2011 to 2024). A carcinoma that arises from epithelial cells of the prostate gland. "Upregulation of IGF1R and/or INSR constitutes a common paradigm mediating tumor resistance in different cancer types and is associated with poor prognosis in prostate cancer, squamous cell lung cancer, and prostate cancer." (PMID 34065119, 2021). "A similar finding from Ofer’s group demonstrated that knockdown of INSR reduced cell growth and proliferation of prostate cancer cell, as well as driving cells into apoptosis." (PMID 38874510, 2024). "In vitro and in vivo experiments suggest that both IGF-1R and INSR promote angiogenesis in prostate cancer." (PMID 36755926, 2023). "IGF2 can activate the IGF1 receptor or insulin receptor or hybrids of these two receptors to contribute to prostate cancer progression to castration resistance." (PMID 25332874, 2014). "Also, formononetin targeted insulin receptor and zinc-alpha-2-glycoprotein which play important roles in metabolisms of tissue cells of prostate cancer." (PMID 38874510, 2024). "In prostate cancer, the induced expression of INSR could increase cell proliferation, colony formation, migration, invasion and resistance to apoptosis in prostate cancer cells through the cooperation with IGF1R." (PMID 38874510, 2024). "This occurs through set up of Epidermal Growth Factor Receptor (EGFR) and Insulin Receptor (InR) dependent autocrine loops, a phenomenon that, considering human data, could be relevant for prostate cancer." (PMID 32385236, 2020). "In our analysis, we also predicted the formononetin’s targets such as INSR and AZGP1 to control the metabolisms in the tissue cell of prostate cancer." (PMID 38874510, 2024). "In the immune cell cluster of prostate cancer, formononetin targeted CD74, TNF, HBB, THBS1, INSR, CXCR4, and HSP90AA1." (PMID 38874510, 2024). "In the case of human prostate cancer cell lines (PC3 and LNCaP), 24‐hrs treatment with IGF1 and insulin reduced (or tended to reduce) the expression of IGF1R, INSR and GHR, whereas only insulin increased the expression levels of Igfbp3 in LNCaP cells." (PMID 28244645, 2017). "Recent reports have identified previously unappreciated crosstalk in prostate cancer cells between the AR pathway and PI3K signalling pathway, the major signalling pathway activated downstream of the INSR." (PMID 22548055, 2012). "Besides, GATA2 is a pioneer transcription factor for androgen receptor (AR) in prostate cancer, and increased GATA2 and its AR-independent transactivation of IGF2 could mediate taxane resistance through the activation of IGF1/insulin receptor signaling." (PMID 30935420, 2019).
Rabson-Mendenhall syndrome (23 papers, 2011 to 2026). Rabson-Mendenhall syndrome belongs to the group of extreme insulin-resistance syndromes (which also includes leprechaunism, the lipodystrophies, and the type A and B insulin resistance syndromes). "There are several, albeit rare, severe diseases of insulin resistance, including leprechaun’s disease, Rabson-Mendenhall syndrome, or type A insulin resistance syndrome, where insulin binding is severely reduced due to mutations in the insulin receptor gene." (PMID 37056675, 2023). "Differential diagnosis of the disorders that share mutations in the INSR gene, include type-A insulin resistance syndrome, Rabson Mendenhall syndrome,and DS." (PMID 40041273, 2023). "Mutation of the insulin receptor gene is responsible for Rabson-Mendenhall syndrome (RMS) which is an autosomal recessive disorder." (PMID 29082893, 2018). "Rabson-Mendenhall syndrome (RMS) is an autosomal recessive disorder due to mutations in the insulin receptor gene (INSR) which is mapped to 19p13.2." (PMID 28663160, 2017). "Genetic studies revealed a homozygous missense mutation in the Insulin receptor gene confirming the diagnosis of Rabson Mendenhall syndrome." (PMID 27891155, 2016). "Differential diagnosis of these disorders that share mutations in the INSR gene, include type-A insulin resistance syndrome, Rabson Mendenhall syndrome and DS." (PMID 26871809, 2016). "There are only two cases where the ratio drops below 1: an autoimmune disease with insulin receptor antibody formation and Rabson–Mendenhall syndrome." (PMID 35324747, 2022). "The SNP in INSR can manifest several insulin-resistant syndromes like Leprechaunism, Rabson-Mendenhall syndrome, and type A insulin resistance." (PMID 27840822, 2016). "This study shows a correlation between SNPs in the INSR gene and several diseases like insulin-resistant syndromes such as Leprechaunism, Rabson-Mendenhall syndrome, and type A insulin resistance." (PMID 27840822, 2016).
lipodystrophy (22 papers, 2013 to 2025). A congenital or acquired disorder characterized by abnormal loss or redistribution of the adipose tissue in the body. "Mendelian genetic studies have identified rare variants in genes such as PPARG, a master regulator of adipocyte differentiation, and INSR, the insulin receptor, associated with lipodystrophies and extreme forms of central body fat distribution." (PMID 40912257, 2025). "It is well known that insulin plays a crucial role in both adipogenesis and lipogenesis, and the deletion of the constitutive insulin receptor (IR) in adipocytes causes lipodystrophy." (PMID 37834368, 2023). "From the 1970s onwards, severe hyperandrogenism was observed in particularly extreme forms of IR, including those due to genetic insulin receptor deficiency and anti-insulin receptor autoantibodies, and those associated with lipodystrophy." (PMID 33901270, 2021). "Generalized lipodystrophies can be mistaken for insulin receptor mutations or acromegaly/gigantism, while familial partial lipodystrophy (FPLD) may be confused with Cushing's syndrome, truncal obesity, and multiple symmetric lipomatosis." (PMID 40154074, 2025). "This group includes mice with adipose-specific deficiency of the insulin receptor, or of Raptor/mTORC1, both of which develop lipodystrophy, and mice with adipose-specific overexpression of RBP-4 which show adipose tissue inflammation with macrophage infiltration." (PMID 29232702, 2017). "Our analyses show that metreleptin and thiazolidinediones appear to lower HbA1c, triglycerides, and body weight in patients with lipodystrophy of all genotypes, and rhIGF-1 appears to lower HbA1c in patients with INSR-related IR." (PMID 37794082, 2023). "To test the therapeutic potential of LPD, we treated a lipodystrophy mouse model IR FKO (adipose-specific insulin receptor knockout) in this study." (PMID 37034803, 2023). "Metreleptin and Thiazolidinediones appear to improve metabolic markers in lipodystrophy, and rhIGF-1 appears to lower HbA1c in INSR-related IR." (PMID 37794082, 2023). "Based on case reports, case series and narrative reviews, rhIGF-1 is now commonly used in neonates with extreme IR due to biallelic INSR mutations, although, unlike metreleptin in lipodystrophy, this use is still unlicensed." (PMID 37794082, 2023). "This was first noted in people with insulin receptor mutations, but more recently, has been described in SHORT syndrome, in which the lack of fatty liver and dyslipidaemia is particularly striking given concomitant lipodystrophy." (PMID 32439336, 2020). "A further 29 patients (10%) had SIR without lipodystrophy, insulin receptor autoantibodies, or a confirmed genetic diagnosis, but suspected to be of monogenic etiology (“idiopathic SIR”)." (PMID 33901270, 2021). "Furthermore, it has recently been demonstrated that adrenal hyperandrogenemia but not ovarian hyperandrogenemia is mediated by insulin receptor signaling in insulin-resistant women with lipodystrophy." (PMID 40944006, 2025).
lung carcinoma (21 papers, 2011 to 2025). "A potential link between the insulin signaling pathway and lung cancer came from a study showing that overexpression of the insulin receptor in lung cancer is associated with increased risk of metastasis and decreased survival." (PMID 24212773, 2011). "BMS-754807, with dual IGF-1R/InsR tyrosine kinase inhibition, has promising anti-tumor activity against various cancers, including breast, pancreatic, and lung cancers." (PMID 39773329, 2025). "INSR has been proved to be abnormally expressed in a variety of tumor tissues, such as breast cancer, lung cancer, and gastric cancer." (PMID 36245982, 2022). "Recently, PGRMC1 has been reported to interact with the insulin receptor and to regulate glucose uptake in lung cancer cells." (PMID 32887925, 2020). "In tobacco carcinogen induced lung cancer mice, the inhibition of insulin like growth factor 1 receptor/insulin receptor (IGF- 1R/IR) by metformin decreased the downstream signaling through Akt pathway." (PMID 27004404, 2016). "The differential expression status of the insulin receptor isoforms in NSCLC patients was confirmed using qRT-PCR assays with lung cancer cDNA arrays and primary tumor samples." (PMID 24571613, 2014). "Additionally, research has shown that nuclear localization of the insulin receptor can promote lung cancer cell proliferation." (PMID 40017690, 2025). "Interestingly, the IGF axis is a complex molecular network (including peptide‐ligands IGF1, IGF2, and insulin, and the receptors IGF1R, IGF2R, and INSR) that is involved in a wide variety of neoplasms such as prostate, breast, colorectal, and lung cancers." (PMID 34668636, 2022). "Additionally, metformin was found to possibly underlie its ability to prevent the development of lung cancer by reducing circulating levels of IGF-I and insulin and mediate its effects through inhibition of the IGF-I/insulin receptor signaling and receptor tyrosine kinases (RTK) signal pathways." (PMID 27105507, 2016). "Hyperglycemia promotes the advancement of lung cancer through high levels of insulin receptor expression, and the IGF-1/IGF-1R pathway is known to play an essential role in the pathogenesis of lung cancer." (PMID 38468345, 2024). "INSR and IRS-1 are both overexpression in lung cancer tissues, and IRS-1 expression had a significant positive correlation with PD-L1 expression." (PMID 36245982, 2022). "The expression of INSR and IRS-1 in 45 cases of nonsmall cell lung cancer and 30 cases of adjacent normal lung tissues was detected by immunohistochemical staining." (PMID 36245982, 2022). "Spearman rank correlation was used to analyze the correlation between INSR, IRS-1, and PD-L1 expressions in nonsmall cell lung cancer." (PMID 36245982, 2022). "Therefore, it is of great significance to explore the correlation between the expression levels of INSR, IRS-1, and PD-L1 and reveal the potential mechanism of insulin pathway-related receptors in the occurrence and development of lung cancer." (PMID 36245982, 2022). "Recently, it has been reported that PGRMC1 directly interacts with insulin receptor (IR) in lung cancer cells, but PGRMC1 knockdown did not change the phosphorylation of Akt, which is downstream of IR30." (PMID 32887925, 2020). "Moreover, ceritinib, which is approved for anaplastic lymphoma kinase (ALK) positive lung cancer, can also inhibit IGF1R and INSR." (PMID 31480400, 2019). "Moreover, IGF signaling has been previously involved in keeping human lung cancer cell stemness while IGF1R downregulation, in conjunction with INSR inhibition, was more effective in blocking IGF- and insulin-mediated signaling and growth in cancer cells compared to single-receptor targeting alone." (PMID 27861515, 2016). "The results showed that INSR and IRS-1 are expressed in both lung cancer and adjacent normal tissues." (PMID 36245982, 2022).
Hypertension (20 papers, 2012 to 2024). The presence of chronic increased pressure in the systemic arterial system. "It is well known that hypertension is associated with oxidative stress and inflammatory responses, leading to the production of specific cytokines and free radicals that disrupt insulin receptor signaling." (PMID 38017521, 2023). "In this regard, it is plausible to consider changes in the expression levels of INSR in PBC as an early molecular marker of future alterations frequently associated with hypertension." (PMID 31064394, 2019). "In the current study, neither the mHFD nor the mCD10d offspring group responded with changes in MAP or RSNA when the InsR antagonist was administered ICV or into the VMH suggesting little role of insulin in mediating the hypertension or sympatho-excitation." (PMID 34248679, 2021). "MetS include a cluster of metabolic abnormalities such as obesity, hypertension, and dyslipidemia, and this condition is related to InsR." (PMID 32252239, 2020). "This protein likely has an inhibitory effect on receptor tyrosine kinase signaling and thus on the insulin receptor signaling pathway, through which GRB14 variants may exert their effect on the development of hypertension." (PMID 22479346, 2012). "We also observed significant within-gene interactions in INSR for SBP, DBP, and hypertension in the simulated data set." (PMID 27980660, 2016). "Some hypertension-related genes exhibited high deletion frequency, including NPPA, ADD1, and INSR." (PMID 35513851, 2022). "Similarly, the pathway-based 2-locus epistasis analysis indicated significant interactions between INSR and PRKCG for SBP and MAP; INS and PIK3R2 for DBP; PIK3CD and ATP1B2 for hypertension in the real data set." (PMID 27980660, 2016). "The most significant interactions for real phenotypes were those between different genes, for example, INS vs. PIK3R2 for DBP, whereas for simulated phenotypes there were significant within-genes interactions such as in INSR gene for SBP, MAP, and hypertension." (PMID 27980660, 2016).
depression (17 papers, 2012 to 2025). "For example, the relevance of insulin receptor signaling in the brain was demonstrated in a brain-specific insulin receptor knockout mouse model establishing the importance of insulin signaling for dopamine turnover, reduction of which was associated with depression and anxiety." (PMID 40575266, 2025). "Existing studies have shown that the key metabolic changes caused by inflammation are an important factor leading to insulin receptor dysfunction, which further has a major impact on the metabolism of the brain and promotes the occurrence and development of mental diseases including depression." (PMID 37032915, 2023). "Concurrently, inflammatory cytokines like IL-1β and TNF-α induce serine phosphorylation of insulin receptor substrates, establishing a molecular bridge between inflammation, depression, and metabolic dysfunction." (PMID 40904459, 2025). "In chronic stress‐induced mouse models of depression (defined by reduced reward sensitivity), insulin receptor sensitizers restored their normal sugar‐water preference and increased subunit expression of NMDA receptors in the hippocampus." (PMID 32281722, 2020). "Insulin receptor knockout mice have elevated levels of monoamine oxidases A and B, resulting in increased dopamine conversion and age‐related anxiety and depression‐like behaviour." (PMID 32281722, 2020). "Compounds enhancing neuronal insulin receptor-mediated transmission exert an antidepressant-like effect in several pre-clinical paradigms of depression; similarly, such properties for DS were found with a stress-induced anhedonia model." (PMID 25767439, 2015). "Central insulin receptor signaling is important in brain function/dysfunction including cognitive disorders, stress response, and depression." (PMID 25767439, 2015). "Antisense RNA targeting the insulin receptor in rats results in increased depression-like behavior and anxiety-like behavior." (PMID 25225489, 2014). "Meanwhile, antidepressant drugs may exert beneficial effects on the insulin receptor phosphorylation pathway through the Shc1/Grb2 complex, which further supports the potential use of Sch1 for depression drug development." (PMID 37649561, 2023). "Less is known about the function of the insulin receptor and its effect on depression and HRQoL." (PMID 34732766, 2021). "Both types of depression were associated with lowered HRQoL regardless of genetic markers for different expression of the insulin receptor gene network." (PMID 34732766, 2021). "Insufficient insulin receptor signalling may be a contributing factor to the development of depression." (PMID 32281722, 2020). "Central insulin receptor-mediated signaling is attracting the growing attention of researchers because of rapidly accumulating evidence implicating it in the mechanisms of plasticity, stress response, and neuropsychiatric disorders including depression." (PMID 25767439, 2015). "Consequently, this further highlights the enhancement of insulin receptor signaling as a potential target of pharmacotherapy of depressive disorder, while exactly how this mechanism results due to the effects of DS reported here, remains to be discovered." (PMID 25767439, 2015). "Our data suggest that dicholine succinate has an antidepressant-like effect, which might be mediated via the up-regulation of hippocampal expression of IGF2, and implicate the neuronal insulin receptor in the pathogenesis of stress-induced depressive syndrome." (PMID 22989159, 2012). "Here we studied whether ZDF rats also innately develop depression, what a correlation is between depression and T2D, whether insulin receptor (IR) expression is involved in, and whether transcutaneous auricular vagus nerve stimulation (taVNS) would be beneficial in amelioration of the comorbidity." (PMID 25365428, 2014).